ABCG2 (ATP binding cassette subfamily G member 2 (JR blood group))
Diseases named in the same sentence as ABCG2 in open-access papers (continued):
Sharing a sentence is not in itself a finding about the gene and the disease.
neutropenia (10 papers, 2014 to 2024). A decrease in the number of neutrophils found in the blood. "However, in other studies, ABCG2 rs2231142 was associated with severe thrombocytopenia, and patients carrying the ABCG2 rs2231142 AA genotype were more likely to develop thrombocytopenia, neutropenia, and HFS even after adjustment." (PMID 33762959, 2021). "We observed significant associations of FLT3 738T (OR=2.7), ABCB1 1236T (OR=0.3), ABCB1 3435T (OR=0.1), ABCB1 2677T (OR=0.4), ABCG2 421A (OR=0.3) alleles and ABCB1 3435, 1236, 2677 TTT haplotype (OR=0.1) on neutropenia." (PMID 26244574, 2015). "There are also no studies regarding the association between the 421C>A mutation in ATP-binding cassette sub-family G member 2 (ABCG2) and the occurrence of severe neutropenia in CPT-11-treated patients with gynecological cancers." (PMID 24932285, 2014). "There is a strong association of the FLT3 738T genotype with leucopenia; FLT3 738T, ABCB1 1236T, ABCB1 3435T, ABCB1 2677T, ABCG2 421A alleles and the ABCB1-3435-1236-2677 TTT haplotype with neutropenia; and primary resistance and inferior survival with the ABCB1-3435-1236-2677 TTT haplotype." (PMID 34948113, 2021). "The present study indicated that the ABCG2 421C>A mutation exerted no affect on the occurrence of CPT-11-induced G4 neutropenia." (PMID 24932285, 2014). "For this reason, the presence of missense SNP in ABCG2, concomitant with other variants in renal drug transporters (SLC29A1 and ABCC4) in heterozygous, could affect the clinical drug efficacy in terms of risk of neutropenia." (PMID 39508043, 2024). "Here, we evaluated additional SNPs on the candidate genes: CYP3A4*22, GSTP1, ERCC2, SLCO1B1, and ABCG2, but did not observe a significant relationship with neutropenia and neurotoxicity except for XRCC3 316A>G rs1799794 for GG+AG alleles (p = 0.03)." (PMID 29163177, 2017). "Therefore, it is important to continue to assess the significance of the variations in ABCG2 and CPT-11-induced neutropenia." (PMID 24932285, 2014).
renal carcinoma (10 papers, 2009 to 2023). A carcinoma arising from the epithelium of the renal parenchyma or the renal pelvis. "One weak association was that the BC resistance protein (BCRP/ABCG2) was under regulation of miR-212-3p in renal cancer cells, the regulation of miR-212-3p in BC was merely mentioned." (PMID 33187481, 2020). "In renal carcinoma cell lines, ABCG2 gene inactivation was found to be connected with the formation of a repressor complex in the CpG island, which was dependent on DNA methylation." (PMID 37445716, 2023). "ABCG2 promoter methylation data have been shown for the five renal cancer cell lines, for 274 patients from the TCGA cohort, and for 16 patients from the own cohort." (PMID 33066132, 2020). "Moreover, a recent study investigated the same CpG sites of the ABCG2 promoter showing differences in methylation levels between three renal carcinoma cell lines." (PMID 24380367, 2013). "Therefore, our aim was to investigate mutations in the coding region for the transmembrane domain 3 and the surrounding domains of ABCG2 in numerous renal cancer samples." (PMID 23467750, 2013). "In renal cancer cell lines, aberrant promoter methylation of the ABCG2 gene was shown and multiple SNPs have been reported in patients with renal cancer, but no direct analyis of tumor tissue samples or a direct association with resistance to tyrosine kinase inhibitors has been reported." (PMID 23467750, 2013).
schizophrenia (10 papers, 2012 to 2025). A major psychotic disorder characterized by abnormalities in the perception or expression of reality. "The Abcg2 mRNA expression of placenta from schizophrenia-like rats was significantly increased on gestation day 18, 20 and 21 compared to the control groups." (PMID 41322281, 2025). "An efflux transporter, ABCG2, was lower, while mRNAs encoding VE-cadherin and ICAM1 were higher in schizophrenia brain." (PMID 30214039, 2020). "The exacerbated decrease in ABCG2 in the “high inflammation” schizophrenia subgroup is consistent with evidence showing that treatment with IL-1β, IL-6 and TNFα reduces both mRNA and protein expression of endothelial ABCG2 in vitro." (PMID 30214039, 2020). "The “high inflammation” schizophrenia subgroup had lower ABCG2 and higher ICAM1, VE-cadherin, occludin and interferon-induced transmembrane protein mRNAs compared to both “low inflammation” schizophrenia and “low inflammation” control subgroups." (PMID 30214039, 2020). "Our findings reinforce the need for future studies to more closely examine the relationship between SNPs in ABCB1 and ABCG2 and cannabis-related psychiatric problems such as addiction, schizophrenia and panic disorder." (PMID 22536451, 2012). "In rats with schizophrenia, placental Abcg2 mRNA expression increased from gestation day 18–21, while BCRP expression increased on all gestation days, but it was only significant on gestation day 20, which is probably caused by the varied post-transcriptional or post-translational processes." (PMID 41322281, 2025). "In contrast, previous candidate gene studies in Caucasian children with ASD and adults with schizophrenia have linked reduced RIS efflux with other ABC transporter subtype mutations (ABCG2_c.421C>A in ABCG2; c.3435C>T, c.1199G>A, c.1236C>T and c.2677G>T in ABCB1)." (PMID 38375040, 2024). "Lower levels of ABCG2 especially in the context of elevated inflammation may result in less capacity to filter out and remove unwanted molecules in the prefrontal cortex for some people with schizophrenia." (PMID 30214039, 2020). "DNA was isolated from the peripheral blood samples of 27 patients with schizophrenia receiving clozapine maintenance treatment, and the pharmacokinetics‐related genes (CYP1A2, CYP2B6, CYP2C19, CYP2D6, CYP3A5, ABCG2, and SLCO1B1) were genotyped." (PMID 40740505, 2025). "Of the genes with significantly lower expression in males with schizophrenia, several were related to energy metabolism (ATP5B, ATP5A1, MRPL23, AFG3L2, ABCG2)." (PMID 26818902, 2016). "We investigated the effects of age, sex, and genetic polymorphisms in CYP isoforms (CYP1A2, CYP2B6, CYP2C19, CYP2D6, and CYP3A5) and drug transporters (ABCG2 and SLCO1B1) on the plasma concentrations of clozapine, N‐desmethylclozapine, and clozapine N‐oxide in Japanese patients with schizophrenia." (PMID 40740505, 2025).
malignant glioma (9 papers, 2010 to 2024). A grade III or grade IV glioma arising from the central nervous system. "Both endothelial cells and malignant glioma cells have been reported to express high levels of ABC transporters, specifically P-glycoprotein (P-gp) (encoded by the—ABCB1 gene), ABCG2 and ABCC4." (PMID 38589905, 2024). "Melatonin can also improve the efficiency of temozolomide therapy by downregulation of the expression and function of the ABC transporter ABCG2/BCRP in malignant gliomas." (PMID 36428458, 2022). "Since ABCG2 is responsible for elimination of porphyrins from living cells, reduced expression of ABCG2 can facilitate the accumulation of PpIX in malignant glioma cells." (PMID 24310600, 2011). "Taken together, it is strongly suggested that both up-regulation of CPOX and down-regulation of ABCG2 are important factors involved in the high accumulation of PpIX in certain cancer cells, including malignant glioma cells." (PMID 24310600, 2011). "Besides, melatonin (N-acetyl-5-methoxytryptamine) increased methylation levels of the ABC transporter ABCG2/BCRP promoter, promoting a synergistic toxic effect with TMZ on GSCs and A172 malignant glioma cells." (PMID 33762015, 2021).
Thrombocytopenia (9 papers, 2014 to 2025). A reduction in the number of circulating thrombocytes. "For example, rs2231142 in the ABCG2 mutant-type (A/A) is significantly associated with sunitinib-induced severe thrombocytopenia, whereas rs2622604 in the ABCG2 mutant-type (T/T) is significantly associated with irinotecan-induced severe myelosuppression." (PMID 38026963, 2023). "In the current meta-analysis, we found that compared with the C allele, the ABCG2 rs2231142 A allele was significantly associated with an increased risk of sunitinib-induced thrombocytopenia in Asians." (PMID 33762959, 2021). "There was no heterogeneity between studies assessing the relationships of the ABCG2 rs2231142 polymorphism with sunitinib-induced thrombocytopenia (I2 = 0, p > 0.05), and the fixed-effects model was applied to the analysis." (PMID 33762959, 2021). "The ABCG2 rs2231142 A allele was associated with an increased risk of sunitinib-induced thrombocytopenia and hand-foot syndrome (HFS) in Asians (ES = 1.65, 95% CI = 1.15–2.36, p = 0.006; ES = 1.52, 95% CI = 1.02–2.27, p = 0.041)." (PMID 33762959, 2021). "The current study is the first study to evaluate both clinical and genetic variable, ABCG2 421C>A, that were associated with sunitinib-induced thrombocytopenia in the Japanese population." (PMID 26914831, 2016). "In the univariate analysis, both age (P = 7.77x10-3, odds ratio (OR) = 1.04, 95%CI = 1.01–1.07) and ABCG2 421C>A (P = 1.87x10-2, OR = 1.71, 95%CI = 1.09–2.68) showed association with sunitinib-induced severe thrombocytopenia." (PMID 26914831, 2016). "Our study suggested that age and ABCG2 421C>A (Q141K) functional variant are significantly associated with sunitinib-induced severe thrombocytopenia." (PMID 26914831, 2016). "The finding of this study is in agreement with a recent study reported from Korean population with 65 RCC patients who received sunitinib therapy, which also reported a significant association of ABCG2 421C>A with grade 3 and grade 4 thrombocytopenia (P-value = 0.04, OR = 9.90)." (PMID 26914831, 2016). "The AUC value utilizing the two parameters (age and ABCG2 421C>A variant) is 0.648, which indicates that the current prediction model required further improvement by identifying additional clinical and genetic factors associated with sunitinib-induced severe thrombocytopenia." (PMID 26914831, 2016). "ABCG2 421C>A could explain part of the inter-individual variability of sunitinib-induced severe thrombocytopenia." (PMID 26914831, 2016). "Genotyping for ABCG2 rs2231142, ABCB1 rs1128503 and rs2032582 polymorphism could become a clinical routine practice to select the appropriate dose to decrease the risk of sunitinib-induced thrombocytopenia and HFS in Asians while ensuring efficacy." (PMID 33762959, 2021). "Female, furosemide, rs1801133, ABCG2 rs2231142, ABCC2 rs717620 were related to more thrombocytopenia, while rs1045642 and high ALB were related to less." (PMID 40832604, 2025). "Analysis of the laboratory data of those with the ABCG2 gene polymorphism showed that the early-onset of lymphocytopenia and elevated LDH tend to be seen in patients with the ABCG2 variant allele, but not thrombocytopenia." (PMID 28335742, 2017).
viral infection (9 papers, 2014 to 2023). "Previous studies have shown that acute viral infection at GD17-18, modelled through use of poly(I:C), decreases the gene expression of placental Abcb1a/Abcb1b and Abcg2 in rats." (PMID 35715474, 2022). "Bacterial and viral infection results in a decrease in ABCG2 and BCRP in the EVT and a concomitant increase in EVT migration, suggesting that BCRP plays a role in infection-related alterations in EVT function." (PMID 31561453, 2019). "Exposure to ssRNA, which models viral infections and induces trophoblast pro-inflammatory responses via the activation of TLR8 and non-TLR8 signaling pathways, also decreased ABCG2 mRNA and BCRP protein expression in EVTs." (PMID 31561453, 2019). "Given the relatively high incidence of bacterial and viral infections during early human pregnancy and its impact on BCRP expression, we determined the role of ABCG2 and BCRP in modulating the migration potential of EVTs, which is critical for the establishment of placentation in early pregnancy." (PMID 31561453, 2019).
mastitis (8 papers, 2009 to 2024). Inflammation of breast tissue during lactation or postpartum due to an obstructed duct or infection. "As far as we are concerned, this is the first study revealing SNPs in SELL, ABCG2, SLC11A1, FEZL, SOD1, CAT, GPX1, and AhpC/TSA genes as candidates for mastitis tolerance/susceptibility in Holstein and Brown Swiss dairy cows." (PMID 35737346, 2022). "In the present study, a real-time PCR was carried out to quantify the mRNA level of SELL, ABCG2, SLC11A1, FEZL, SOD1, CAT, GPX1, and AhpC/TSA genes in tolerant and susceptible Holstein and Brown Swiss dairy cows to mastitis." (PMID 35737346, 2022). "PCR-DNA sequencing of SELL, ABCG2, SLC11A1, FEZL, SOD1, CAT, GPX1, and AhpC/TSA revealed nucleotide sequence variations in the form of SNPs associated with mastitis tolerance/susceptibility in investigated Holstein and Brown Swiss dairy cows." (PMID 35737346, 2022). "Although there is little information on SELL, ABCG2, SLC11A1, and FEZL gene polymorphisms and their association with mastitis susceptibility in dairy cattle, previous studies reported this association in one breed using RFLP and SSCP genetic markers with opposing results." (PMID 35737346, 2022). "Although, there is little information on SELL, ABCG2, SLC11A1, and FEZL genes polymorphisms and their association with mastitis susceptibility in dairy cattle, previous studies reported these association in one breed using RFLP and SSCP genetic markers with opposing results." (PMID 35737346, 2022). "Consequently, the aim of the current work was to revealing the association of SNPs and expression profile of SELL, ABCG2, SLC11A1, FEZL,SOD1,CAT,GPX1, and AhpC/TSA genes with mastitis tolerance/susceptibility in Holstein and Brown Swiss dairy cows." (PMID 35737346, 2022). "In addition, using PCR-DNA sequencing of immunological (SELL, ABCG2, FEZL, and SLC11A1) markers from the investigated Holstein and Brown Swiss dairy cows, nucleotide sequence alterations in the form of SNPs related to mastitis tolerance/susceptibility were found." (PMID 37756095, 2023). "The significance of the LOC407171, PTPRC, ABCG2, and IDH1 genes in the turquoise module was confirmed using DT models and attribute weighting, highlighting their critical roles in mastitis." (PMID 34691146, 2021). "Consequently, SELL, ABCG2, SLC11A1, FEZL, SOD1, CAT, GPX1, and AhpC/TSA regulation mechanisms are well understood in the mastitis tolerant and affected Holstein and Brown Swiss dairy cows." (PMID 35737346, 2022). "However, many of the most differentially regulated genes, e.g. ABCG2 and FKBP5, have not, to our knowledge, previously been associated with mastitis." (PMID 23324411, 2013).
Stroke (8 papers, 2012 to 2024). Sudden impairment of blood flow to a part of the brain due to occlusion or rupture of an artery to the brain. "To further analyze the difference between ABCG2 rs2231142 variants and CVD, we examined the association of ABCG2 rs2231142 with self-reported CAD and stroke using the same database." (PMID 39315221, 2024). "In concordance to our in vitro data, own in vivo stroke studies revealed that Abcg2 protein expression of total brain samples was significantly decreased after 1 h tMCAO followed by 24 h reperfusion in male C57Bl/6 mice (unpublished data)." (PMID 25389390, 2014). "In case of Abcg2 few data exist about its regulation in vivo after stroke." (PMID 25389390, 2014). "ABCC5 and ABCG2 showed elevated expression after ischemia in a rat model for stroke." (PMID 22553972, 2012). "In contrast, there was a significant upregulation of ABCG2 and BCRP protein levels 3–14 days after induction in a rat in vivo stroke model." (PMID 38737275, 2024).
colon adenocarcinoma (7 papers, 2020 to 2023). "For colon adenocarcinoma, the only significant association was found between ABCG2 expression level and microsatellite instability (p = 0.020)." (PMID 37445716, 2023). "For the colon adenocarcinoma, the level of methylation was negatively correlated with the expression for 5 of 14 probes across the ABCG2 gene (Pearson correlation coefficients ranging from −0.132 to −0.117)." (PMID 37445716, 2023).
endometrial cancer (7 papers, 2017 to 2024). Primary or metastatic malignant neoplasm involving the endometrium (mucous membrane that lines the endometrial cavity). "Although multispecific ABCs have been in the focus of anticancer research and increased expression of ABCG2 has been reported in breast cancer, data about their expression in endometrial cancer are limited to cell line Ishikawa only." (PMID 33917029, 2021). "Among the ABC genes, there were mutations in all four genes involved in the efflux of steroid conjugates (i.e., ABCC1, ABCC4, ABCC11, ABCG2), in 5.7–8.3% of patients with endometrial cancer." (PMID 28674494, 2017). "Moreover, in endometrial cancer, ABCG2 is expressed in the Ishikawa model cell line, which is enriched in CD133 and has cancer stem cell characteristics." (PMID 28674494, 2017). "Among the steroid-transporting ABC-transporters, ABCG2 has been observed at the mRNA and protein levels in CD133+ Ishikawa endometrial cancer cells, which have characteristics of cancer stem cells." (PMID 28674494, 2017). "Endometrial CSCs isolated from endometrial cancer expressing stemness markers, including SOX2, OCT4, MYC, ABCG2, NES, and NANOG, have been demonstrated to show greater expansion potential and colony-forming capabilities, as well as to express self-renewal genes." (PMID 38539419, 2024).
head and neck cancer (7 papers, 2011 to 2024). A primary or metastatic malignant neoplasm affecting the head and neck. "Lastly, knockdown of Sox2 using siRNA in head and neck cancer was found to result in a down-regulation of ABCG2, a CSCs marker known to be associated with chemo-resistance." (PMID 29401647, 2018). "In head and neck cancer, ABCG2 protein expression correlates with pack-years of tobacco use and cisplatin resistance." (PMID 38256106, 2024). "The correlation between ABCG1 (P = 0.00715) or ABCG2 (P = 0.0573) expression and poor prognosis of patients suffering from head and neck cancer was found with an endpoint of relapse-free survival." (PMID 30364132, 2018). "Moreover, in vitro, exposure to tobacco smoke condensate up-regulates ABCG2 in head and neck cancer cell lines leading to an increase in cisplatin resistance." (PMID 33469038, 2021).
protoporphyria (7 papers, 2010 to 2023). "A mouse model of erythropoietic protoporphyria when intercrossed with the ABCG2 deficient mouse showed reduced protoporphyrin IX levels in the skin that protected against erythropoietic protoporphyria-associated toxicity." (PMID 37438132, 2023). "Several studies have confirmed this role on ABCG2-null mice where these animals are more susceptible to diet-induced protoporphyria and phototoxicity, caused by the accumulation of pheophorbide, a chlorophyll degradation product, and a confirmed ABCG2 transport substrate." (PMID 33670777, 2021). "On the other hand, ABCG2-knockout mice are extremely sensitive to the dietary chlorophyll-breakdown product pheophorbide a, which suggests that ABCG2 expressed in the small intestine plays a critical role in reducing the risk for developing diet-dependent phototoxicity and protoporphyria." (PMID 21188243, 2010). "Abcg2-knockout mice developed protoporphyria with increased PpIX in erythrocytes and plasma, suggesting the involvement of Abcg2 in PpIX transport." (PMID 37106683, 2023). "Of note, animal models of erythropoietic protoporphyria suggest a role for ABCG2 in cytoprotective porphyrin transport, mirroring a likely protective role for ABCG2 as a physiological porphyrin transporter in hematopoietic stem cells." (PMID 32978801, 2020).